VIP (vasoactive intestinal peptide)
Diseases named in the same sentence as VIP in open-access papers (continued):
Sharing a sentence is not in itself a finding about the gene and the disease.
pancreatic cancer (12 papers, 1997 to 2025). "No consistent increase in the proliferation rates of colon and pancreatic cancer cell lines was seen when adding exogenous VIP to cancer cells in vitro, and, in certain cell lines, exogenous VIP even inhibited growth." (PMID 37444395, 2023). "There were minimally significant differences in VIP expression between normal and pancreatic cancer tissue (p = 0.012) and increased ZEB1 expression in cancer tissue." (PMID 37444395, 2023). "Eotaxins were reported induced in the cerulein-induced CP in mice; whereas, another eosinophils chemoattractant neuropeptide VIP was reported in the human pancreatic cancer." (PMID 34183442, 2021). "Similarly, human PDAC patients with pancreatic cancer had significantly higher plasma VIP levels than healthy volunteers, suggesting that plasma VIP is a potential biomarker for PDAC." (PMID 36302761, 2022). "Herein we show that pancreatic cancers overexpress vasoactive intestinal peptide, and pharmacological inhibition of its signaling significantly enhances responsiveness of pancreatic ductal adenocarcinoma to immune checkpoint therapy, thus improving overall survival in mouse models." (PMID 36302761, 2022). "Clinical studies show that radiolabeled VIP analogues localize breast cancer, pancreatic cancer, intestinal adenocarcinomas, neuroendocrine tumors, and colorectal cancer using a combination of positron emission tomography (PET) and computed tomography (CT) scans." (PMID 31559013, 2019). "Conversely, no specific binding of VIP was detected in control pancreata but was identified in 3 of 12 pancreatic cancer specimens." (PMID 9166939, 1997). "Interestingly, various solid tumors, including breast, lung, and pancreatic cancers, ectopically express neuropeptides such as Neuropeptide Y (NPY), Substance P (SP), and Vasoactive Intestinal Peptide (VIP), mediating communication between neurons, immune cells, and cancer cells." (PMID 40805163, 2025). "Moreover, stimulation of adenylyl cyclase and the PKA pathway by forskolin and vasoactive intestinal peptide (VIP) increased MUC5AC antigen expression and release from pancreatic cancer cells suggesting that PKA may contribute to the up-regulation of MUC5AC expression seen in PanIN1A." (PMID 24281201, 2010).
myopia (11 papers, 2008 to 2025). "Furthermore, it is proposed that atropine may regulate myopia by modulating the signaling pathways associated with VIP." (PMID 38279089, 2024). "Understanding VIP’s role in regulating eye growth and preventing myopia opens potential avenues for developing VIP-based therapies to maintain normal circadian rhythms and eye growth, enhancing current myopia management strategies." (PMID 40933557, 2025). "The findings of elevated VIP mRNA and protein levels observed in the FDM group indicate the potential involvement of VIP in the pathogenesis and progression of myopia." (PMID 38279089, 2024). "Future studies should further delineate the mechanism of interactions between atropine and VIP and their impacts on the eye and the visual cortex during myopia development." (PMID 38279089, 2024). "Recently, studies based on different animal models of myopia, including monkeys, chickens, and mice, revealed that the VIP signal cascade mediates the occurrence and development of myopia." (PMID 38279089, 2024). "Among those genes was vasoactive intestinal polypeptide (VIP), which is expressed in a subset of amacrine cells, and its downregulation in response to myopia has been shown in macaque retinas, chick retinas and chick retina/RPE complex." (PMID 39876870, 2024). "This study aimed to investigate the potential involvement of vasoactive intestinal polypeptide (VIP) in myopia development and its contribution to the mechanism of action of the anti-myopia drug, atropine." (PMID 38279089, 2024). "The increase in VIP concentration post surgery is affected by corneal ablation, which is determined by the degree of myopia before surgery." (PMID 37081425, 2023). "Insulin-like growth factor-1 and vasoactive intestinal peptide also play a significant role in myopia." (PMID 36418970, 2022). "VIP influences myopia development through several mechanisms." (PMID 40933557, 2025). "VIP also alters the expression of genes involved in eye growth and myopia." (PMID 40933557, 2025). "Additionally, we have identified the retinal VIP signaling pathway as a crucial target for preventing and managing myopia." (PMID 38279089, 2024). "In addition, it has been observed to decrease the growth of myopia progression and axial length elongation while restoring the expression of retinal VIP to normal levels." (PMID 38279089, 2024). "As a result, atropine could regulate myopia development via several pathways in the eye and visual cortex, with VIP perhaps serving as a central signaling molecule in this process." (PMID 38279089, 2024). "We hypothesize that VIP plays an essential role in the formation of myopia, and its expression changes during the occurrence and development of myopia." (PMID 38279089, 2024). "Furthermore, our study has shed light on the involvement of VIP in visual development and the regulatory role of atropine in myopia." (PMID 38279089, 2024). "Consequently, investigating the interaction between the retinal signaling molecule VIP and the anti-myopia drug atropine promotes the identification of new therapeutic targets and insights for the prevention and treatment of myopia." (PMID 38279089, 2024). "The findings of this study indicate that augmented expression of VIP may plays a role in the onset and progression of myopia." (PMID 38279089, 2024). "Ablation of the anterior corneal stroma aimed at changing the refraction of myopia could injure the parasympathetic nerves present in it, inhibit the release of VIP, and lead to an elevated difference in tear VIP concentration after both surgeries." (PMID 37081425, 2023). "The EGR1 gene is expressed in the amacrine cell of the retina and was shown to respond to optical defocus in a sign-of-defocus sensitive manner, while VIP is the principal neurotransmitter of the VIPergic amacrine cells of the retina, which were shown to be involved in myopia development." (PMID 34107987, 2021).
myopia (continued). "Therefore, we selected EGR1, FOS, JUN, VIP and VIPR2 as functional candidates and investigated their potential association with high myopia." (PMID 23637909, 2013). "Atropine's ability to control myopia may be due to direct regulation of retinal VIP levels." (PMID 38279089, 2024). "EGR1, JUN, FOS and VIP are unlikely to be important in predisposing humans to high myopia." (PMID 23637909, 2013). "Experimental models have shown that VIP can influence gene expression related to ECM remodeling, cell proliferation, and differentiation, contributing to myopia’s development or prevention." (PMID 40933557, 2025).
osteoarthritis (11 papers, 2014 to 2023). A noninflammatory degenerative joint disease occurring chiefly in older persons, characterized by degeneration of the articular cartilage, hypertrophy of bone at the margins and changes in the synovial membrane. "In rheumatic diseases, an association between low VIP levels in serum and worse outcomes in patients with RA and SpA22,23 and joint damage in osteoarthritis patients has been reported." (PMID 29391448, 2018). "VIP recombinant plasmid can alleviate osteoarthritis effectively via inhibiting NF-κB signaling pathway." (PMID 29540226, 2018). "Decreased expression of VIP was recently reported in the synovial fluid of patients with osteoarthritis (OA) and poor radiological progression, indicating a protective role for VIP." (PMID 24409325, 2014). "VIP has recently been identified as a potential target for the treatment of osteoarthritis (OA)." (PMID 34016131, 2021). "Antagonists that inhibit VIP activity may prove beneficial in the alleviation of osteoarthritis pain." (PMID 31023212, 2019). "Osteoarthritis was effectively treated by VIP via inhibiting the NF-κB signaling pathway." (PMID 29540226, 2018). "Finally, VIP may in some way contribute to osteoarthritis progression and pain development in this disease, although this relationship is not entirely clear." (PMID 35566735, 2022). "Interestingly, the VAS score correlated positively with MOD values of CGRP, SP, and VIP, and negatively with MOD values of NPY in all patients, although a significantly higher expression was observed in patients with osteoarthritis." (PMID 35566735, 2022).
pancreatic neuroendocrine tumor (11 papers, 2013 to 2025). Pancreatic endocrine tumor, also known as pancreatic neuroendocrine tumor (PNET), describes a group of endocrine tumors originating in the pancreas that are usually indolent and benign, but may have the potential to be malignant. "Everolimus was also trialled (without success) because of the possible antisecretory and antitumoral effect shown in pancreatic neuroendocrine tumors secreting VIP." (PMID 40520658, 2025). "Almost 1% of the whole cohort had malignant VIPoma, which makes VIP-secreting tumors a rare entity even within the subgroup of functional pancreatic NETs." (PMID 39845312, 2024). "The tumor of the prostate is diffusely positive for NKX3.1 (a prostate marker) and displays single-cell nuclear positivity for synaptophysin, but negativity for VIP and Islet‐1, a marker for pancreatic neuroendocrine tumors (PanNET)." (PMID 33398457, 2021). "Vipoma is a rare pancreatic NET that produces vasoactive intestinal peptide, an important peptide in the neuromodulation of intestinal function." (PMID 28194228, 2017). "Functional tumors secrete bioactive substances such as insulin, glucagon, vasoactive intestinal peptide (VIP), and gastrin in cases of pancreatic NETs (pNETs) or 5-hydroxyindoleacetic acid (5-HIAA) in cases of small bowel NETs, which can lead to clinical syndromes, such as the carcinoid syndrome." (PMID 41010726, 2025).
allergic disease (10 papers, 2011 to 2025). An immune response that occurs following re-exposure to an innocuous antigen, and that requires the presence of existing antibodies against that antigen. "The detected upregulation of VIP in allergy could contribute to allergic rhinorrhea whereas a loss of VIP-activated secretion in patients with CF may impair mucociliary transport, contributing to increased incidences of sinonasal infections and rhinosinusitis." (PMID 25504259, 2015). "The role of nerve cell-derived VIP has been implicated in promoting eosinophilic inflammation in allergic diseases, so we hypothesized that VIP, along with eotaxin, may have a role in the accumulation of eosinophils and mast cells in each segment of the esophagus in human EoE." (PMID 38391908, 2024). "Because VIP serves a variety of biological purposes, VIP analogs and/or antagonists may offer improved therapeutic alternatives for treating allergic diseases." (PMID 38331782, 2024). "Therefore, our study aimed at investigating the relationship between stressful life events, neuropeptides (SOM, VIP, SP), Th1/Th2 regulation and allergic sensitization as well as the relationship between these life events and allergic disease (atopic eczema)." (PMID 31826043, 2018). "As VIP is also related to allergic sensitization, our results suggest that VIP might be involved in the development of stress-related allergic diseases." (PMID 31826043, 2018). "Better understanding of the VIP-Treg system may pave the way to use VIP as an adjunct or replacement for allergy immunotherapy, a treatment for allergic asthma." (PMID 22126441, 2011). "Current evidence suggests that the expression of VIP specific receptors, including VPAC2 and chemoattractant receptor–homologous molecule expressed on Th2 cells (CRTH2) receptor on MCs and basophils, provides an opportunity for VIP to act on these cells and promote allergic disease pathogenesis." (PMID 33239034, 2020).
epilepsy (10 papers, 2014 to 2025). A brain disorder characterized by episodes of abnormally increased neuronal discharge resulting in transient episodes of sensory or motor neurological dysfunction, or psychic dysfunction. "VIP IN-mediated disinhibition has additionally been implicated in diseases like epilepsy." (PMID 38706517, 2024). "Our results indicate that very few specific subtypes of PV, SST, and VIP neurons make predominant contributions to the pathology of epilepsy." (PMID 40313715, 2025). "This suggests the possibility of harnessing VIP IN long-term plasticity to control activity-related neuropathologies such as epilepsy." (PMID 38706517, 2024). "The unique functions of VIP neurons relative to other inhibitory subgroups position them as critically important players in the pathology of neurodevelopmental disorders, including epilepsy." (PMID 40313715, 2025). "As VIP INs are able to mediate disinhibition, they are ideally positioned as key regulators of activity in local circuits, with implications for disease states such as epilepsy." (PMID 38706517, 2024). "Increased inhibition to VIP bipolar cells in epilepsy may reflect an effort to compensate for hyperexcitation, e.g., OLM cells may strive both to disinhibit themselves and increasingly inhibit principal cells." (PMID 34819310, 2021). "At least, they should better discuss the possibility that enhanced intrinsic excitability of VIP interneurons in epilepsy may account for the reduced activation of OLM interneurons." (PMID 34819310, 2021). "On the other hand, VIP levels were elevated in serum and CSF of children with seizure disorders." (PMID 24705860, 2014). "VIP can enhance the electrical activity of neurons in many brain regions and could therefore play a role in seizure disorders." (PMID 24705860, 2014). "Other neuropeptides such as nesfatin-1 and vasoactive intestinal peptide have been less studied in this field; however, as nesfatin-1 levels change over the course of epilepsy, this can be considered as an interesting marker to diagnose patients who have suffered a recent epileptic seizure." (PMID 24705860, 2014). "Consequently, the protective role of VIP IN→MC LTD might be possible to harness as a therapy for epilepsy." (PMID 38706517, 2024). "VIP IN dysregulation may thus lead to neuropathologies such as epilepsy." (PMID 38706517, 2024). "RTN2, also a VIP in E-DE network module C, is a regulator of the glutamate transporter EAAC1; the dysregulation of EAAC1 was reported in animal models of epilepsy and in the hippocampus of TLE patients." (PMID 26011637, 2015).
gastric cancer (10 papers, 2013 to 2024). A primary or metastatic malignant neoplasm involving the stomach. "It has been reported that endogenous VIP affect the growth of some gastric cancer cells by binding to G-protein-coupled receptors." (PMID 24228003, 2013). "So we wonder that if VIP, which was secreted by gastric cancer cells, facilitate gastric cancer cells to escape immunosurveillance by inhibiting NK cells activity." (PMID 24228003, 2013). "Then we analyzed the effect of VIP and its antagonist on the cytotocicity of NK cell to gastric cancer cells and on expressions of NKG2D, DAP10, and NF-κB signal molecules in NK cells." (PMID 24228003, 2013). "Moreover, the inhibitory effects on the apoptosis pathway observed in gastric cancer suggest potential roles for VIP and ZEB1 in modulating cell survival mechanisms in this specific cancer type." (PMID 37444395, 2023). "Additionally, in gastric cancer, VIP and ZEB1 showed inhibitory effects on the apoptosis pathway (FDR < 0.05)." (PMID 37444395, 2023). "So, gastric cancer cells might escape organism immune cleaning by secreting VIP to inhibit NKG2D signal pathway of NK cells." (PMID 24228003, 2013). "Many studies showed that VIP was related with the gastric cancer." (PMID 24228003, 2013). "Our finding provide a new insight into the importance of VIP in gastric cancer progression." (PMID 24228003, 2013). "So, we suppose that VIP, which is secreted by gastric cancer cells, may facilitate gastric cancer cells to escape organism immune cleaning by inhibiting NKG2D signal molecules in NK cells." (PMID 24228003, 2013). "Thus, VIP antagonists may be helpful for the study of anticancer drugs in patients with gastric cancer." (PMID 30813924, 2019). "We had showed that some gastric cancer cells in tumor tissues could secrete VIP." (PMID 24228003, 2013). "GSA revealed that VIP and ZEB1 had activating effects on EMT and inhibitory effects on the cell cycle pathway in both colon and gastric cancers." (PMID 37444395, 2023). "Ca2+ signaling is required for the carcinogenesis and progression of gastric cancer, and activation of VIPR1 by VIP can stimulate TRPV4-mediated Ca2+ entry." (PMID 36157238, 2022). "More intriguingly, in gastric cancer, VIPR1/TRPV4/Ca2+ signaling stimulates VIP secretion, enforcing a positive feedback loop in promoting cancer progression." (PMID 35864952, 2022). "The results of immunohistochemistry showed that the protein expression levels of RBP7, DES, SPP1, VIP, and PRKCG in gastric cancer tissues were higher than those in normal tissues, while PNOC, TNFRSF12A, and TUBB3 proteins are less expressed in gastric cancer tissues than normal tissues." (PMID 35174205, 2022).